MTOR (mechanistic target of rapamycin kinase)
Diseases named in the same sentence as MTOR in open-access papers (continued):
Sharing a sentence is not in itself a finding about the gene and the disease.
myopathy (28 papers, 2011 to 2024). A disease of the muscle in which the muscle fibers do not function properly. "Our data show that mutation of VCP/p97 in IBMPFD disrupts mTOR signaling, a serine/threonine kinase that contributes to myopathy and which has been showing to worsen the severity of the disease." (PMID 37602234, 2023). "Muscle-specific mTOR knockout caused decreased postnatal growth, due to the reduced size of fast muscle fibers and severe myopathy." (PMID 35126176, 2021). "Changes in the mTOR signaling pathway (e.g., the loss of mTOR in skeletal muscle) or alterations to mTOR-mediated processes can contribute to myopathy and other skeletal muscle pathologies." (PMID 32391060, 2020). "AICAR has also been shown to alter mTOR signaling pathway in skeletal muscle and our previous study demonstrated that WB myopathy is associated with mTOR dysmetabolism-induced hypoxia." (PMID 32851035, 2020). "Constitutive, muscle‐specific knockout of raptor or mTOR causes a severe, early‐onset myopathy that eventually causes the death of the mice." (PMID 31697050, 2020). "Genetic deletion of the mTOR inhibitor TSC1 in mice (which causes hyper activation of mTOR) results in a late-onset myopathy, which is related to impaired autophagy." (PMID 32635462, 2020). "Muscle-specific raptor knockout mice (RAmKO) and raptor and rictor double-knockout mice (DmKO) show myopathy similar to one associated with the loss of mTOR in muscle, whereas muscle-specific rictor knockout mice (RImKO) do not." (PMID 29089899, 2017). "Like Raptor knockouts, mTOR-deficient muscles develop a myopathy reminiscent of muscular dystrophy, together with impaired oxidative metabolism." (PMID 21798082, 2011). "In addition, an increase in mTOR inhibition was shown to worsen the myopathy associated with the disease, suggesting that the accumulation of autophagosomes that cannot proceed to full maturation is more harmful than impaired autophagy." (PMID 37602234, 2023). "Indeed, mTOR deficiency leads to reduced muscle dystrophin content and causes dystrophic defects leading to severe myopathy." (PMID 36402791, 2022). "Furthermore, the late‐onset myopathy described in muscle‐specific TSC knockout mice was linked to the mTOR‐dependent inhibition of autophagy through ULK1, and the pathology was reminiscent of that in autophagy‐deficient muscle." (PMID 28130275, 2017). "Upon the removal of the kinase mTOR from the skeletal muscle, a similar late-onset of myopathy was observed, which was accompanied by premature death." (PMID 36016684, 2022). "Knocking out mTOR has been shown to lead to progressive myopathy because skeletal muscle mass and function are affected." (PMID 35497980, 2022). "In GNE myopathy, Aβ deposition triggers autophagy, and rapamycin is an inducer of autophagy, an mTOR inhibitor that can promote the clearance of protein aggregates and reduce the toxic effect of Aβ." (PMID 35904705, 2022). "Downstream of AKT, mTOR is an important regulator of protein synthesis and regulation of autophagy and decreased mTOR signaling in skeletal muscle leads to severe myopathy." (PMID 33243288, 2020). "In a previous study, we have shown that hypoxia and the activation of its upstream mediators (AKT/PI3K/mTOR) played a key role in WB myopathy, and supplementation of quantum blue (QB) can help to reduce WB severity via modulation of hypoxia-related pathways." (PMID 32851035, 2020). "Conditional loss of mTOR concomitant with the expression of kinase-inactive mTOR results in early onset, rapidly progressing myopathy that impairs growth and leads to juvenile lethality." (PMID 32635462, 2020). "For instance, muscle-specific inactivation of mTOR leads to severe myopathy, resulting in premature death." (PMID 29736257, 2017). "Muscle-specific mTOR knockout mice (mTOR-) exhibit severe myopathy leading to premature death between 22 and 38 weeks of age." (PMID 29089899, 2017).
myopathy (continued). "A cautionary note on the excessive mTOR activation, at least in skeletal muscle, comes from the study, in which sustained activation of mTORC1 by genetic TSC deletion caused late‐onset myopathy." (PMID 28130275, 2017). "The myopathy was more severe in mTOR knockout than in Raptor knockout mice, possibly due to reduction in the content of dystrophin and other components of the dystrophin-glycoprotein complex." (PMID 21798082, 2011). "However, in skeletal muscle rapamycin-induced inhibition of mTOR has been shown to impair myogenic differentiation, blunt the anabolic response to overload and nutrients, with muscle-specific inactivation of mTOR leading to myopathy." (PMID 25866088, 2015). "Syndecans are involved in several signaling pathways, including ERK/MAPK, AKT/mTOR/S6K1, and Wnt signaling; however, none of them have previously been investigated in the context of WB myopathy." (PMID 38130476, 2023). "The phosphorylated levels of AKT at Ser473 site, mTOR at Ser2481 site, and PI3K P85 at Tyr458 site, as well as their mRNA levels were significantly increased in breasts (affected caudal area, WW and apparent healthy area, WN) of broilers with WB myopathy compared to their healthy counterparts." (PMID 31632293, 2019).
gastrointestinal tumors (25 papers, 2014 to 2025). "Our team's prior work has emphasized the heightened activation of the mTOR pathway in gastrointestinal tumors, where it governs metabolism, fostering cell survival and proliferation." (PMID 39048994, 2024). "We show significantly increased cyclin-dependent kinase activities in GI tumors, which suggests increased proliferation (taken together with pathways found enriched at whole-protein and RNA abundance) and decreased MTOR activity in these tumors." (PMID 38703764, 2024). "A gastrointestinal tumor-based bioinformatics analysis revealed that the canonical apoptosis-related pathways ErbB and mTOR signalling were identified as pathways regulated by m1A-related enzymes." (PMID 37173310, 2023). "Under this theme, the PI3K/Akt/mTOR signalling pathway is a central regulator of cell metabolism and survival, and during colon carcinogenesis, the pathway is abnormally hyperactivated, whilst the expression of its endogenous inhibitor, PTEN, declines." (PMID 35326689, 2022). "Recently, leptin was shown to contribute to mucin production and the formation of gastrointestinal neoplasms by modulating mTOR-, STAT3-, and ERK-dependent pathways in addition to PKC-, PI3K-, and MAPK-dependent pathways." (PMID 26839577, 2016). "For instance, miR-129-5p influences various diseases ranging from digestive tumors to neurodegenerative disorders by modulating different genes and pathways including WNT/β-catenin and PI3K/AKT/mTOR." (PMID 38673905, 2024). "Expression of activated forms AKT, MEK, mTOR, p70 and STAT3 in the GI tumor cells used in this study each showed a significant partial protection of cells from [curcumin + sildenafil] induced cell death, abolishing the cell-death potentiating effect of sildenafil." (PMID 29245915, 2017).
bacterial infection (23 papers, 2013 to 2025). "As metabolism through glycolysis and PPPare stimulated through mTOR signaling,it follows that susceptibility to bacterial infection mediated by mTOR inhibitorsmay be due to defects in radical oxygen and nitric oxide production byphagocytes." (PMID 38767353, 2024). "Assuch, it is well-known in the clinic that patients taking mTOR inhibitors haveincreased susceptibility to bacterial infection, often in the skin and soft tissues(12, –, 16)." (PMID 38767353, 2024). "We also demonstrated that B+I injury, compared to sham injury, increases susceptibility to bacterial infections late after injury and our data here indicate that this susceptibility is also regulated by mTOR." (PMID 35955914, 2022). "It is well accepted that the mTOR axis regulates inflammation and innate immune cell function, and we hypothesized that mTOR regulates systemic and local hyper-responses to burn and B+I injury and, thus, influences susceptibility to bacterial infections." (PMID 35955914, 2022). "Cytokine and chemokine signaling, inducible nitric oxidesynthase, and p65 nuclear translocation were present at similar levelsduring mTOR suppression, suggesting an NF-κB-independent role formTOR signaling in the immune response during bacterial infection." (PMID 38767353, 2024). "These experiments support a metabolic role for mTOR in the production ofphagocyte free radicals and clearance of bacterial infection." (PMID 38767353, 2024). "The clear defectin the control of nitric oxide-sensitive Staphylococcus whenmTOR is suppressed demonstrates that mTOR signaling plays a central role in freeradical-dependent clearance of bacterial infection." (PMID 38767353, 2024). "This is in agreement with a study that indicated that inactivation of mTOR can sensitize the proapoptotic response to bacterial infection." (PMID 34944759, 2021). "mTOR pathway has also been reported to promote innate immunity against bacterial infections in mammals." (PMID 31921198, 2019). "The TSC1/2 heterodimer, a key upstream regulator of the mTOR, can inhibit the activation of mTOR, which plays a critical role in immune responses after bacterial infections." (PMID 27746591, 2016). "Notably, research conducted with dairy cows has shown that viral and bacterial infections can trigger the activation of the PI3K/Akt/mTOR pathway." (PMID 40063888, 2025). "The functional enrichment analysis revealed that the eQTLs examined were primarily associated with glycerolipid metabolism and the expression of key metabolic factors influenced by bacterial infections (Vibrio cholerae and Helicobacter pylori) as well as the mTOR signaling pathway." (PMID 38426052, 2024). "Here, we show the essential role for mTOR signaling in theimmune response to bacterial infection." (PMID 38767353, 2024). "The functional enrichment analysis revealed that the eQTLs identified are primarily involved in Glycerolipid metabolism and the expression of key metabolic factors regulated by bacterial infections (Vibrio cholerae and Helicobacter pylori) and the mTOR signaling pathway." (PMID 38426052, 2024). "In bioinformatics analysis, bacterial infections (Vibrio cholerae and Helicobacter pylori) and mTOR signaling pathways may mediate the glycerol lipid metabolism process involved in PsA." (PMID 38426052, 2024). "In addition, inhibition of mTOR by rapamycin resulted in higher bacterial numbers further supporting the role of mTOR in the control of bacterial infection." (PMID 31832425, 2019). "However, it is also reported that inhibition of the mTOR pathway with rapamycin has immunostimulatory effects on blood leukocytes from transplant recipients or on mouse myeloid cells after bacterial infection." (PMID 28489580, 2017). "However, the mTOR pathway is known to be activated in phagocytes in response to bacterial infection or exposure to LPS." (PMID 27367858, 2016).
bacterial infection (continued). "Moreover, bacterial infections and mTOR-mediated activation of metabolic factors may play an important role in this process." (PMID 38426052, 2024). "Thus glutamine might activate the mTOR signaling pathway to inhibit the autophagy responses during bacterial infection." (PMID 35052548, 2021). "However, the impact of bacterial infection on mTOR signaling remains unclear." (PMID 28932706, 2017). "Unexpected TMA, more associated with viral (EVM/CMV) than bacterial infections and triggered by acute/chronic active ABMR and mTOR inhibitor-CNI combination even though it was not statistically significant." (PMID 37730583, 2023). "Furthermore, we describe Nrf2/Keap1/AREs, PI3K/Akt/mTOR, and TLR signaling as the main signal transduction pathways of oxidative stress during bacterial infections." (PMID 34746124, 2021). "To investigate whether mTOR inhibitor, rapamycin, could alter bacterial-induced autophagy, we treated both TSC1 WT and KO BMMφ with rapamycin 1 h prior to bacterial infection with TB and BCG." (PMID 27387347, 2016).
brain disorder (20 papers, 2014 to 2025). A disease affecting the brain or part of the brain. "For instance, mimicking DEPDC5 (DEP containing 5 domain) loss-of-function in zebrafish recapitulates critical hallmarks of brain disorders caused by mutations in this gene, such as epileptiform discharges and exacerbated mTOR signaling." (PMID 35875659, 2022). "mTOR signaling, involving mTORC1 and mTORC2 complexes, critically regulates neural development and is implicated in various brain disorders." (PMID 33976205, 2021). "Dysregulation of mTOR is a hallmark of a wide variety of brain disorders, and inhibition of mTOR is associated with Aβ-peptide-related synaptic dysfunction in AD." (PMID 29091582, 2017). "Knowledge on physiological functions of mTOR would also be important to understand the mTOR-dependent mechanisms whereby circadian dysfunction is involved in the pathogenesis of brain diseases." (PMID 36045116, 2022). "Cul4B has been recently identified to play an important role in regulating TSC2 and mTOR signaling in some brain diseases, and it is also able to degrade 4E-BP2 eukaryotic translation initiation factor." (PMID 33384682, 2020). "Accumulating evidence indicates that mTOR is dysregulated in various brain diseases, and inhibition of mTOR by rapamycin provides neuroprotective effects." (PMID 24602288, 2014). "It has also been shown that interventions to either buffer consequences of oxidative phosphorylation defects (e.g. redox imbalances) or reduce energetic demands (e.g. via mechanistic target of rapamycin (mTOR) inhibition) can delay brain disease and extend life in the mouse." (PMID 34656053, 2022). "Importantly, mTOR activities are often found dysregulated in brain diseases where the daily rhythms in patients are disrupted." (PMID 36045116, 2022). "Moreover, Tanc2 modulations promoting or suppressing mTOR signaling have therapeutic potential for the treatment of various mTOR-related peripheral and brain disorders." (PMID 33976205, 2021). "In keeping with this, mTOR (mammalian Target of Rapamycin) which is a main upstream regulator of both ATG and UP, has been widely implicated in synaptic plasticity and DA-related brain disorders." (PMID 30186112, 2018). "Disorders within the mTOR and MAPK pathways are characteristic of patients with ASD (e.g., an increase in protein p-EIF4E, rpS6, ERK1–2 in blood) and are an important target in the search for a treatment for this brain disease." (PMID 34579089, 2021).
benign tumors (19 papers, 2011 to 2025). "Heterozygous TSC1/2 mutations have been causatively linked to hyperactivation of the mammalian target of rapamycin (mTOR) pathway, leading to the aberrant cell growth and proliferation characterizing benign tumors in LAM." (PMID 32365712, 2020). "The mutation causes unregulated activation of the mammalian target of rapamycin (mTOR) pathway with development of benign tumors in multiple organs such as the kidneys, brain, liver, heart and skin." (PMID 25258166, 2014). "These proteins form a complex that regulates the mammalian/mechanistic target of rapamycin (mTOR), and the hyperactivation of mTOR, caused by loss of TSC1 or TSC2, is involved in the formation of benign tumors." (PMID 41341265, 2025). "Meanwhile, our results, together with those of previous studies, suggested that other processes such as oncogene-induced senescence attenuate the changes in the downstream of PI3K/Akt/mTOR pathway in these benign tumors." (PMID 27992366, 2017). "In TSC, the growth of benign tumors in various organs occurs from loss of TSC1 or TSC2 genes and subsequent overactivation of mammalian target of rapamycin (mTOR), a kinase responsible for regulating cell growth, proliferation, and angiogenesis." (PMID 27351628, 2016). "In humans, loss of the TSC protein results in a disorder characterized clinically by the growth of benign tumors in multiple organs, due to overactivation of mTOR inhibition." (PMID 21415462, 2011). "For example, patients with tuberous sclerosis complex (TSC), caused by mutations in the tumor suppressor genes TSC1 or TSC2 leading to mTOR hyperfunction, show heterogeneity of benign tumors and cellular dysplasia in multiple organs, including astrocytomas and cortical tubers in the brain." (PMID 27655340, 2016).
inflammation (17 papers, 2012 to 2025). Aberrant reaction of the microcirculation characterized by movement of fluid and leukocytes from the blood into extravascular tissues. "In RA, inflammatory cytokines interact with the mTOR signaling pathway, enhancing disease activity and increasing synovial inflammation, osteoclast differentiation, and joint destruction." (PMID 40589696, 2025). "Meanwhile, inhibition of the PI3K/Akt/mTOR pathway can further promote autophagy and inhibit eosinophilic inflammation." (PMID 38888464, 2024). "Coumarin compound, emodin, alleviated LPS-induced pulmonary inflammation in rat lung tissues through inhibiting the mammalian target of rapamycin (mTOR)/hypoxia-inducible factor 1-alpha (HIF-1α)/vascular endothelial growth factor (VEGF) signaling pathway." (PMID 35002723, 2021). "Combined, these data suggest involvement of autophagy-mediated degradation in pulmonary inflammation-induced muscle atrophy through mTOR inhibition and FoXO1 activation, in addition to UPS-mediated proteolysis." (PMID 29720191, 2018). "A recent study regarding hyperoxia induced ALI also revealed that pretreatment with Alda-1 reduced hyperoxia induced immune cell infiltration, alveolar damage and lung inflammation and preserved alveolar permeability through the activation of Akt and mTOR pathways." (PMID 34764958, 2021). "The consequences above indicated that mTOR myeloid specific ablation contributed to an elevated number of Eops in asthmatic mice, therefore leading to accelerated eosinophil development and enhanced levels of eosinophilic airway inflammation." (PMID 29720621, 2018). "Having determined an important role for mTOR in the induction of TH2 cell cytokine production, we sought to examine the function of this signaling pathway in the induction of airway inflammation by IL-33 in vivo." (PMID 22738676, 2012). "In line with previous observations in the related model of pulmonary inflammation, protein synthesis signaling through the IGF-1/Akt/mTOR pathway is reactivated 48 h following LPS in the muscle of WT animals, which signified initiation of muscle mass recovery in that study." (PMID 36807882, 2023). "It is worth mentioning that mTOR was found to be able to activate NF-κB and signal transducer and activator of transcription 3 (STAT3) through the formation of immunoproteasomes, both of which play a significant role in the pathogenesis of cardiac inflammation and fibrosis." (PMID 40867548, 2025).